TRPV4 (transient receptor potential cation channel subfamily V member 4)
Diseases named in the same sentence as TRPV4 in open-access papers (continued):
Sharing a sentence is not in itself a finding about the gene and the disease.
brachyolmia (8 papers, 2009 to 2024). Brachyolmia is a rare, clinically and genetically heterogeneous group of bone disorders characterized by short trunk, mild short stature, scoliosis and generalized platyspondyly without significant abnormalities in the long bones. "It is also important to note that R616Q mutation in TRPV4, has been associated with brachyolmia in humans, a rare bone disorder suggesting that an over-active cholesterol insensitive TRPV4 plays a role in this disease." (PMID 38333595, 2024). "The goal of this study was to elucidate the molecular mechanisms underlying how two TRPV4 gain-of-function mutations lead to strikingly distinct severities of skeletal dysplasias (i.e., moderate brachyolmia vs. lethal metatropic dysplasia)." (PMID 36810131, 2023). "Interestingly, TRPV4 has gained medical and clinical interest since mutations in the TRPV4 gene can result in genetic disorders like Brachyolmia, Charco-Marie Tooth type 2C, spinal muscular artrophy and hereditary motor and sensory neuropathy type 2." (PMID 25257900, 2014). "We propose that AD brachyolmia lies at the mildest end of this spectrum and, since all cases described with this diagnosis and TRPV4 mutations display metaphyseal changes, we suggest that it is not a distinct entity but represents the mildest phenotypic expression of SMDK." (PMID 21658220, 2011). "For example, a V620I substitution (exon 12, G858A) in TRPV4 is responsible for moderate brachyolmia, which exhibits short stature, scoliosis, and delayed development of deformed bones." (PMID 36810131, 2023). "Following the inclusion of dominant brachyolmia in the TRPV4 group, the few remaining short-trunk disorders have been incorporated in the SED group." (PMID 21438135, 2011). "An example of this is the lack of an obvious cartilage development phenotype in TRPV4 targeted mice, however gain of function mutations in TRPV4 can cause Brachyolmia in humans." (PMID 20046828, 2009). "On later revision, the skeletal lesions were not sufficient to be classified as one of the TRPV4-related dysplasias, although some features resembled mild brachyolmia." (PMID 33685999, 2022).
cardiac hypertrophy (8 papers, 2019 to 2026). "In the present study, we found that TRPV4 expression was significantly increased in mice hypertrophy hearts, human failing hearts, and AngII-induced hypertrophic cardiomyocytes, suggesting that TRPV4 was implicated in the processes of cardiac hypertrophy and failure." (PMID 35731090, 2022). "Therefore, in the present study, we aim to investigate the role and the underlying mechanism of TRPV4 in pathological cardiac hypertrophy subjected to pressure overload." (PMID 35731090, 2022). "The interaction of TRPV4 and CaMKII has a major role in cardiac hypertrophy, due to activation of TRPV4 leading to upregulation of Ca2+/CaMKII mediated activation of the NFkB-NLRP3 pathway." (PMID 41555550, 2026). "Compared to wild-type mice, Trpv4 knockout mice showed a remarkable reduction in cardiac hypertrophy, cardiac dysfunction, fibrosis, and inflammation." (PMID 38256251, 2024). "In a recent study, TRPV4 channel expression was found to be significantly increased in the ventricles of mice with left ventricular pressure overload-induced hypertrophy and in failing human ventricles." (PMID 37371124, 2023). "Taken together, our results confirm that TRPV4 activation contributes to cardiac hypertrophy in vitro." (PMID 35731090, 2022). "The evidence supports that TRPV4 plays a key role in mediating CaMKII activation during cardiac hypertrophy development." (PMID 35731090, 2022). "Our results suggest that TRPV4 activation contributes to pressure overload-induced cardiac hypertrophy and dysfunction." (PMID 35731090, 2022). "To evaluate the potential role of TRPV4 in cardiac hypertrophy, we first measured TRPV4 protein and mRNA expression levels in left ventricle (LV) tissue from wild-type (WT) TAC versus sham mice at different time points (2, 7, 14, and 28 days) after surgery." (PMID 35731090, 2022). "Deletion of TRPV4 attenuated transverse aortic constriction (TAC)-induced cardiac hypertrophy, cardiac dysfunction, fibrosis, inflammation, and the activation of NFκB - NOD - like receptor pyrin domain-containing protein 3 (NLRP3) in mice." (PMID 35731090, 2022). "To further investigate the role of TRPV4 in cardiac hypertrophy induced by pressure overload, we performed TAC or sham surgery in WT and TRPV4 knockout (Trpv KO) mice." (PMID 35731090, 2022). "We further evaluated the effects of TRPV4 inhibition with a specific antagonist GSK2193874 (GSK3874) on pathological cardiac hypertrophy and dysfunction induced by pressure overload." (PMID 35731090, 2022). "Interestingly, the pressure overload resulted in reduced cardiac hypertrophy, cardiac dysfunction, fibrosis and inflammation in TRPV4 knockout mice compared to wild-type animals." (PMID 37371124, 2023). "Therefore, inhibiting TRPV4 appears promising to limit CaMKII phosphorylation and its multiple consequences and inflammation in cardiac hypertrophy." (PMID 37371124, 2023). "Our in vitro experiments showed that TRPV4 blockade protected cardiac hypertrophy induced by AngII." (PMID 35731090, 2022). "However, the role of TRPV4 in the development of pressure overload-induced cardiac hypertrophy is not well understood." (PMID 35731090, 2022). "Indeed, the deletion of endothelial TRPV4 has been found to suppress TAC-induced cardiac hypertrophy and dysfunction via increased coronary angiogenesis and reduced cardiac fibrosis." (PMID 35731090, 2022). "Collectively, our findings imply that TRPV4 might be a stress response molecule that is upregulated in cardiac hypertrophy." (PMID 35731090, 2022). "However, further studies are required to investigate the close interaction of TRPV4 with Piezo1 in pathological cardiac hypertrophy." (PMID 35731090, 2022). "Future studies addressing TRPV4 upregulation in the context of cardiac hypertrophy are needed." (PMID 35731090, 2022).
cardiac hypertrophy (continued). "In addition, TRPV4 channel expression is found to be significantly increased in failing human ventricles, and in murine ventricles using a mouse model of pressure overload-induced cardiac hypertrophy." (PMID 38256251, 2024). "Thus, TRPV4 may represent a potential therapeutic drug target for cardiac hypertrophy and dysfunction after pressure overload." (PMID 35731090, 2022). "However, the effects of TRPV4 on pressure overload-induced cardiac hypertrophy remain unclear." (PMID 35731090, 2022). "Therefore, we hypothesized that TRPV4 activation contributes to cardiac hypertrophy through CaMKII." (PMID 35731090, 2022). "We found that AngII-stimulated cardiac hypertrophy, as indicated by increases in cell surface area and the expression of ANP (Nppa) and BNP (Nppb), was largely inhibited by the TRPV4 specific antagonist GSK3874." (PMID 35731090, 2022).
osteoporosis (8 papers, 2011 to 2025). A condition of reduced bone mass, with decreased cortical thickness and a decrease in the number and size of the trabeculae of cancellous bone (but normal chemical composition), resulting in increased fracture incidence. "In bone tissue, TRPV4 has been associated with OC and OC differentiation, pathogenesis of osteoporosis and other metabolic bone diseases." (PMID 36978936, 2023). "Mechanical stimulation of TRPV4 has also been associated with osteoporosis due to its impact on OC survival and the higher osteoporotic fracture risk related to TRPV4 deficiency." (PMID 36978936, 2023). "Conversely, the skeletal dysplasia and osteoporosis also seen in our proband are known to be associated with gain‐of‐function TRPV4 variants." (PMID 30693671, 2019). "The GOF variant in the TRPV4 gene also resulted in increased bone turnover and decreased bone mass, which significantly increased the risk of osteoporosis and bone fractures, known as insufficiency fractures, which mainly occur in the metaphysis of the long bones." (PMID 40258774, 2025). "Mouse studies have demonstrated that Trpv4 knockout increases trabecular bone volume, reduces osteoclast activity, and provides protection against bone loss under conditions such as ovariectomy-induced osteoporosis and mechanical unloading." (PMID 40362247, 2025). "Therapies targeting mechanosensitive pathways, such as modulators of TRPV4 activity or agents that enhance osteocyte mechanosensitivity, may offer novel strategies to prevent or mitigate osteoporosis." (PMID 40362247, 2025). "In addition, TRPV4 knockdown suppressed osteoclast differentiation and osteoporosis induced by ovariectomy through calcium-calcineurin-NFATc1 pathway." (PMID 37608122, 2023). "In any case, the important role of TRPV4 in osteoclast differentiation has been identified and more treatments for osteoclast abnormalities, such as RA or osteoporosis, could be developed, targeting TRPV4 in the future." (PMID 36291594, 2022). "A recent study also indicated that the knockdown of TRPV4 could inhibit osteoclast differentiation and alleviate osteoporosis in mice by inhibiting cellular autophagy as well as regulating NFATc1." (PMID 36291594, 2022). "While TRPV4 apparently acts in adult unloading-induced osteoporosis, this is not a selectable trait during evolution, since animals with weakened bones should have a disadvantage." (PMID 21573172, 2011).
psoriasis (8 papers, 2020 to 2026). An autoimmune condition characterized by red, well-delineated plaques with silvery scales that are usually on the extensor surfaces and scalp. "Moreover, the expression levels of TRPV4 in the skin of three patients correlated positively with the severity of their psoriasis, and psoriasis-induced itch is strongly associated with TRPV4 activation." (PMID 38474002, 2024). "Furthermore, the TRPV4 channel has also been associated to psoriasis, an itching condition characterized by chronic skin inflammation." (PMID 32481620, 2020). "Studies on imiquimod-induced psoriasis have revealed that macrophage infiltration in the skin can be reduced by genetic knockdown of the gene encoding the transient receptor potential cation channel subfamily V member 4 (TRPV4) calcium ion channel as well as by orally administered resveratrol." (PMID 38791342, 2024). "In mouse models of chemically induced psoriasis, Trpv4-knockout mice exhibited milder dermatitis than wild-type mice." (PMID 38474002, 2024). "Overexpression, gain of function, and activation of channels, including nAChR, TRPV1, TRPV3, TRPV4, TRPM4, and ANO1 in keratinocytes, as well as TRPV1, nAChR, Kv1.3, and KCa3.1 in immune cells, have been associated with the induction of psoriasis." (PMID 38474002, 2024). "In this study, we found that TRPV4 expression is decreased in dermal macrophages during AD and psoriasis." (PMID 36645854, 2023). "In psoriasis, dermal macrophages rarely expressed TRPV4 mRNA, whereas the keratinocytes in these specimens did." (PMID 36645854, 2023). "We observed TRPV4 mRNA and macrophage marker proteins in human skin specimens of AD and psoriasis using a combination of FISH and fluorescent immunostaining." (PMID 36645854, 2023). "TRP channels have a pivotal role in the physiology and pathology of the skin, and recently the TRPV4 channel has emerged as a pharmaceutical target for skin disorders like rosacea, ichthyosis, psoriasis, and contact and atopic dermatitis." (PMID 32481620, 2020). "By using an induced psoriasis mice model, it was determined that TRPV4 is overexpressed in DRG neurons isolated from these mice." (PMID 32481620, 2020). "A recent study has shown that TRPV4 is upregulated in both human and mouse psoriasis models." (PMID 38474002, 2024). "The finding that TRPV4 expression correlates positively with the severity of psoriasis and itch suggests that pharmacological modulation of TRPV4 could be a promising therapeutic approach for managing psoriasis-induced itching." (PMID 38474002, 2024). "Growing evidence suggests the involvement of multiple TRP subtypes in the pathogenesis of psoriasis, including altered expression of vanilloid subtypes, such as TRPV1, TRPV3, TRPV4, TRPV6, the canonical TRPC6, and melastatin TRPM8 in patients." (PMID 41689746, 2026). "Specifically, peripheral blood mononuclear cells from individuals with psoriasis exhibit elevated expression of TRP channels such as TRPM2 and TRPV1 and decreased expression of TRPM4, TRPM7, TRPV3, TRPV4, and TRPC6." (PMID 38474002, 2024). "Interestingly, a recent study demonstrated that the expression levels of TRPV4 in the skin are positively correlated with the severity of the psoriasis, yet the itch phenotypes were not assessed in these patients." (PMID 34299208, 2021).
Arthritis (7 papers, 2009 to 2025). Inflammation of a joint. "The increased levels of extra-physiologically activated TRPV1 and TRPV4 channels caused by incubation with TNF-α can significantly contribute to the activation of synoviocytes observed in joint inflammation." (PMID 19695100, 2009). "Given that GSK101 is lethal in vivo, the quest for a therapeutically beneficial (eg, in arthritis, hepatic, or renal disease) TRPV4 activator continues." (PMID 33819485, 2021). "In synoviocytes obtained from rats in a collagen-induced arthritis model, TRPV4 is a key channel in controlling hypotonicity-induced Ca2+ entry and subsequent proliferation of synoviocytes, thus further aggravating the disease state." (PMID 30326593, 2018). "In 2021, researchers confirmed that the TRPV4 mechanosensitive ion channel can induce the accumulation of extracellular ATP at acupuncture points in animal experiments, mediating the analgesic effects of acupuncture in an arthritis rat model." (PMID 41169813, 2025). "Therefore, similar to the current literature concerning TRPM3’s role in arthritis, further studies are warranted to determine whether TRPV4 serves a protective or pro-inflammatory role in arthritis development." (PMID 30326593, 2018). "In summary, the current data suggests that agonism of TRPC5, TRPM3, TRPM8, and TRPV2 may help ameliorate or prevent arthritis, while antagonism of TRPM7 and TRPV4 may have a similar effect." (PMID 30326593, 2018).
arthropathy (7 papers, 2016 to 2025). Any disorder of the joints. "The TRPV4 mutation has long been linked to a range of diseases, including peripheral neuropathies, skeletal dysplasia, and arthropathy, as evidenced by genome analysis." (PMID 39333347, 2025). "Therefore, TRPV4 has critical functions in the formation and maintenance of healthy cartilage and this is reflected by the outcome of TRPV4 mutations, which result in pathogenic skeletal dysplasia and arthropathy." (PMID 33805168, 2021). "TRPV4 was previously associated to musculoskeletal diseases, skeletal dysplasia, and arthropathy." (PMID 32955611, 2021). "We report a TRPV4 variant in a father and son referred with a diagnosis of Thiemann disease and compare the clinical and radiological features of Thiemann disease with Familial digital arthropathy-brachydactyly (FDAB)." (PMID 31248428, 2019). "TRPV4-mediated skeletal dysplasia and arthropathy represent another major TRPV4-related disorders which comprising over hundreds of disorders, often linked to orthopedic complications." (PMID 39333347, 2025).
breast tumor (7 papers, 2013 to 2022). "In line with this, TRPV4 expression was noticeably increased in breast-tumor-derived endothelial cells (B-TECs), and TRPV4 activation with AA or 4αPDD stimulated migration in B-TECs, but not in the control human microvascular endothelial cells." (PMID 36430727, 2022). "Basal-like breast tumors are highly heterogeneous, so to further explore the role of TRPV4 in this cancer type, we interrogated the Red Module by analyzing the gene-ontology of the top 100 most interconnected genes within this cluster." (PMID 33322037, 2020). "A recent study revealed that TRPV4 was dramatically up-regulated in breast tumor-derived endothelial cells (B-TECs) and that TRPV4-mediated Ca2+ entry significantly increased the rate of cell migration as compared to control cells." (PMID 29324706, 2018). "TRPV4 expression is elevated in basal-like breast tumors compared to other molecular subtypes." (PMID 33322037, 2020). "Using the Gene Set Analysis (GSA)-Tumor application to interrogate the expression of TRPV4 in 1881 breast tumor samples, TRPV4 expression was found to be significantly higher in basal subtype compared to the HER2, Lum A and Lum B subtypes of tumors (p < 0.001)." (PMID 27291497, 2016). "AKT was upregulated by TRPV4 in both studies, and AKT activation was strongly involved in gastric and breast tumor metastasis, as in prior studies." (PMID 32843668, 2020). "This analysis revealed that high TRPV4 expression is a significant marker for patients with LN+ basal breast tumors, but not for patients with LN- disease." (PMID 33322037, 2020).
inflammatory bowel disease (7 papers, 2011 to 2025). A spectrum of small and large bowel inflammatory diseases of unknown etiology. "TRPV4 mRNA is highly enriched in colonic sensory neurons and TRPV4 protein is found in colonic nerve fibres from patients with inflammatory bowel disease." (PMID 24288041, 2011). "Although TRPV4 inhibition represents a potential therapeutic option for IBS or inflammatory bowel disease (IBD), directly blocking TRPV4 might negatively affect normal physiological function." (PMID 30365528, 2018). "Interestingly, TRPV4 has a role in gastrointestinal inflammatory diseases such as ulcerative colitis (UC) and Crohn’s disease (CD), which are part of a group of inflammatory bowel diseases (IBD)." (PMID 32033399, 2020). "Transient receptor potential vanilloid-3 (TRPV3) and transient receptor potential vanilloid-type 4 (TRPV4) are indirectly involved in gastrointestinal inflammation from inflammatory bowel diseases because they function as sensors of harmless and non-harmless chemical or physical stimuli." (PMID 34834237, 2021). "However, the colonic mucosa of inflammatory bowel disease patients is infiltrated by TRPV4-positive CD45-positive leukocytes which are absent from the mucosa of healthy controls." (PMID 21420431, 2011).